Y_RNA (Y RNA )
Gene: Miscellaneous RNA gene on chromosome 4 (2,615,124 to 2,615,224, reverse strand). Ensembl gene ENSG00000206738.
Homologues: Orthologues: chimpanzee Y_RNA (99% identical). Paralogues in human: Y_RNA (87% identical), Y_RNA (85% identical), Y_RNA (84% identical), Y_RNA (83% identical), RNY3 (82% identical), Y_RNA (82% identical), RNY3P4 (81% identical), Y_RNA (81% identical), RNY3P1 (80% identical), RNY3P14 (80% identical), Y_RNA (80% identical), Y_RNA (79% identical), and 94 more.